ROCK1 (Rho associated coiled-coil containing protein kinase 1)
Diseases named in the same sentence as ROCK1 in open-access papers (continued):
Sharing a sentence is not in itself a finding about the gene and the disease.
tumor (continued). "However, we did not observe a significant correlation between tumor size and ROCK1 or ROCK2 mRNA expression." (PMID 26468005, 2015). "In addition, patients with weak expression of ROCK1 in the invasive front, but not the central tumour, had lower cancer-specific survival rates, implying that this marker is protective during cancer progression." (PMID 25380619, 2014). "Moreover, we have recently shown that cytoplasmic translocation of p120 controls ILC tumor growth and metastasis through Mrip-dependent regulation of Rock1 signaling, while IDC does not appear to be contingent on these signals for anchorage-independence." (PMID 22662240, 2012). "However, contrary to our findings, the majority of studies are focused on miR124 as a tumor suppressor, and it is generally accepted that miR124 inhibits cell proliferation and metastasis of cancer through suppression of several oncogenes such as STAT3, ROCK1, Slug, and ZEB." (PMID 36358691, 2022). "Taking all of this information into account, we speculate that ROCK1 is likely to be overexpressed in tumor tissues, and that it controls tumor invasion by a negative feedback system, because of the presence of excessive EGFR stimulation and the subsequent ROCK response in cancer cells." (PMID 21722395, 2011). "Noncanonical pathways include RhoA/ROCK1, PI3K/Akt, Wnt/β-catenin, MAPK/p38, or MAPK ERK1/2, all of which mediate different effects of TGF-β on tumor cells." (PMID 34548615, 2021). "Noncanonical pathways include RhoA/ROCK1, PI3K/Akt, Wnt/β-catenin, MAPK/p38 or MAPK ERK1/2, which mediate different effects of TGF-β on tumor cells." (PMID 34548615, 2021). "Similar to our Y27632 findings, the knockout of either ROCK1 or ROCK2 in MDA-MB-231 cells did not affect tumor growth, whereas the intratumoral injection of anti-RhoA siRNA reduced tumor growth." (PMID 29535813, 2018). "The presence of either ROCK1 or ROCK2 was sufficient to support tumour growth, but tumours did not form if both were missing." (PMID 26950944, 2016). "Although cancerous cells were found that contained just one type of ROCK protein, no tumor cells were found that lacked both ROCK1 and ROCK2, further confirming that having one ROCK protein is essential for tumor formation." (PMID 26765561, 2016). "After thorough in vitro characterization of cells lacking ROCK1 and ROCK2, we investigated the roles of ROCK1 and ROCK2 in tumorigenesis in vivo using genetically engineered mouse tumor models." (PMID 26765561, 2016). "Collectively, analysis of ROCK1 and ROCK2 protein expression in tumors and tumor derived cell lines suggests that the absence of ROCK1 and ROCK2 is incompatible with tumorigenesis." (PMID 26765561, 2016). "Using a tumor xenograft system, SVR cells stably expressing non-targeting control, ROCK1, or ROCK2 shRNA plasmids were seeded onto 1 mm2 gelatin sponges and implanted onto the chorioallantoic membrane of 8 day post-fertilization chicken eggs." (PMID 22934846, 2013). "The functional differences for ROCK1 and ROCK2 in tumor and non-tumor cells could be explained by their variations in expression levels, subcellular locations, and interaction partners in individual cell types." (PMID 26725045, 2016).
cancer (180 papers, 2008 to 2026). A tumor composed of atypical neoplastic, often pleomorphic cells that invade other tissues. "Researchers have also linked abnormalities in the ROCK1/LIMK2/cofilin pathway to various types of cancer." (PMID 39596356, 2024). "In ESCC, EGFR-AS1 has been implicated in up-regulating ROCK1 expression by sponging miR-145, thus promoting cancer cell invasion and migration." (PMID 38589454, 2024). "MYBPH was found to suppress Rho-associated coiled-coil containing protein kinase 1 and inhibit actin organization, thus impairing single cell motility, increasing collective cell migration, and reducing cancer invasion and metastasis." (PMID 37812190, 2023). "Rho-associated coiled-coil forming protein kinase 1 (ROCK1) can be combined with activated Rho protein in tumours, promoting the cell actin backbone recombination in cancer, thus, accelerating the cancer cell proliferation and migration." (PMID 37599427, 2023). "ROCK1 has been found to be associated with dozens of cancers such as prostate cancer, laryngeal squamous cell carcinomas, nasopharyngeal carcinoma, osteosarcoma, breast cancer, and gastric cancer." (PMID 36781836, 2023). "We previously found that the Rho-associated kinase 1 (ROCK1) activated Cancer-associated fibroblasts (CAFs) to promote LSCC metastasis." (PMID 36334145, 2022). "ROCK1 overexpression / activation is commonly linked to a more highly metastatic and aggressive phenotype of human cancers." (PMID 35287604, 2022). "According to published reports, ROCK1 overexpression is strongly associated with more highly metastatic and invasive phenotypes in human cancers." (PMID 35865469, 2022). "The serine/threonine kinase protein Rho-associated coiled-coil containing protein kinase 1 (ROCK1) promotes the growth of malignant tumors." (PMID 35651814, 2022). "The abnormal activation of ROCK1 kinase causes several disorders, whereas numerous studies have also shown that RhoA is expressed highly in various cancers, including colon, lung, ovarian, gastric, and liver malignancies." (PMID 36500403, 2022). "ROCK1 plays a role in the metastasis of cellular movement and the accumulation of extracellular matrix in cancer-associated fibroblasts (CAFs), thus demonstrating that it is an important signaling pathway in cancer progression." (PMID 36077069, 2022). "Rho-associate kinase protein-1(ROCK-1) is overexpressed in many types of cancer and is associated with tumor growth." (PMID 34209857, 2021). "HIFs activate transcription of the Rho family member RHOA and Rho kinase 1 (ROCK1) genes, leading to cytoskeletal changes, focal adhesion formation and actomyosin contractions that underlie the invasive cancer cell phenotype." (PMID 34415238, 2021). "Rho-associated protein kinase 1 (ROCK1), a serine/threonine kinase, is critical regulator of development and progression in various human malignant tumors." (PMID 33639865, 2021). "The upregulation of ROCK1 was found in the cancer tissues of BRCA patients, which was associated with poor prognosis outcome." (PMID 31986487, 2020). "ROCK1 was significantly associated with increased cell proliferation as measured by Ki67-LI in all cancers (p<0.0001)." (PMID 31557128, 2019). "Since ROCK1 is involved in proliferation, migration, and invasion of cancer cells, we analyzed protein expression and phosphorylation of key signaling molecules associated with ROCK1." (PMID 28978024, 2017). "ROCK1 mediates the Smad-independent, TGFβ/RhoA signaling axis, and has also been shown to be an important mediator of cancer-associated fibroblast (CAF) activation and deposition of extracellular matrix (ECM) proteins in solid tumors." (PMID 28841710, 2017). "Three of the somatic ROCK1 mutations, which were identified in human cancers, have been further analyzed to determine their functional impact by molecular and cellular approaches." (PMID 26725045, 2016).
cancer (continued). "By multivariate analysis, high ROCK1 expression in the invasive front was independently associated with greater cancer-specific survival (HR 0.3, 95% CI 0.11–0.84, p = 0.0054)." (PMID 25380619, 2014). "Loss of ROCK1 was independently linked to worse cancer-specific survival (p = 0.0054) by multivariate analysis." (PMID 25380619, 2014). "RhoA, ROCK1 and Rac1 proteins are GTPases that regulate F-actin and thereby regulate cancer cell migration and have been implicated in metastasis of several types of cancer including CRC." (PMID 23560089, 2013). "Similar to the activating mutations identified in ROCK1, sequencing of cancer genomes revealed mutations in MRCKα and MRCKβ that would likely increase their specific activity." (PMID 21949762, 2011). "Interestingly, in both DEN-treated and Eμ-Myc transgenic mice, the Rock1 NC mutation apparently had beneficial anti-cancer effects." (PMID 38616733, 2024). "Since PMOP patients had a higher risk to get some types of cancer, we were greatly interested in whether the low expression of ROCK1 made great importance to increasing the cancer risk, accelerating the cancer progression, or worsening the cancer prognosis." (PMID 37683138, 2023). "Indeed, the MAPK/ERK pathway increases caveolin-1 expression in cancer cells and, through the induction of RhoA/Rho-associated protein kinase 1 (ROCK1), promotes cell contraction and favors cancer cell migration along the pre-existing collagen matrix." (PMID 36497384, 2022). "Rho-associated coiled-coil containing kinase 1 (ROCK1) belongs to the family of so-called AGC kinases comprising more than 60 evolutionary related serin/threonine protein kinases including important anti-cancer targets such as AKT, p70S6 kinase, or GSK-3ß." (PMID 31557128, 2019). "Alternatively, this may be due to experimental issues caused by the general ROCK1 up-regulation in ERG positive cancers." (PMID 31557128, 2019). "Association between ROCK1 expression and Ki67-labeling index in all cancers." (PMID 31557128, 2019). "Activating mutations have been identified in ROCK1 in some cancer types." (PMID 28841710, 2017). "Interestingly, we found that ROCK1 up-regulation was linked to higher patient age exclusively in cancers harboring the ERG fusion, suggesting that the consequences of ERG fusion may vary with age." (PMID 31557128, 2019). "MiRNAs have also been reported to regulate the expression of ROCK1 in various physiological conditions other than cancer, such as miR-26a in lung injury, miR-145 in HepG2 cell proliferation, miR-148 in gastritis, and miR-148a in myogenic differentiation." (PMID 40419128, 2025). "Inhibition of ROCK1 has been shown to induce phagocytosis by macrophages or phagocytosis of cancer cells by dendritic cells." (PMID 40419128, 2025). "It has been established that ROCK1 plays a role in cellular motility and promotes cancer cell migration, invasion, and metastasis in various cancers." (PMID 40368918, 2025). "The proteomics study confirmed the enrichment of molecules in fibronectin and the VEGF pathway in PAK4KO cancer cells, along with the upregulation of EphA2, RhoA, ROCK1, ROCK2, and components of the EPH-ephrin signalling pathway, linking to enhanced VM." (PMID 41294859, 2025). "First, we analyzed the gene expression profiles of 33 cancer types from the TCGA database and found that the expressions of ROCK1 and YAP1 were positively correlated." (PMID 40368918, 2025). "Our research discovers that two specific proteins in cancer cells—one that handles copper (ATOX1) and another that controls cell movement (ROCK1)—work together to drive cancer growth." (PMID 40940984, 2025). "Overexpression of ROCK1 and RhoA correlates with cancer progression and plays a pivotal role in determining cancer cell motility and invasion phenotype." (PMID 39354653, 2025).
cancer (continued). "Here, we performed a functional genomics screen using CRISPR-Cas9 library targeting genes with available FDA approved therapeutics and identified ROCK1/2 as a top hit that sensitizes cancer cells to OXPHOS inhibition." (PMID 39345502, 2024). "p-FAK and p-ROCK1/2 are classical pathways that promote the invasion and metastasis of cancer cells." (PMID 38975937, 2024). "ROCK1 is known to be a downstream effector of the RhoA signaling pathway that influences the behavior of cancer cells modulating cell motility and the epithelial-to-mesenchymal transition." (PMID 39000555, 2024). "Compound F08060425 affects key pathways like cytokine signaling and the Adaptive immune system, interacting with genes FLT3, SYK, and ROCK1, indicating its role in immune modulation and potential applications in cancer therapy." (PMID 39286631, 2024). "ROCK1 directly or indirectly regulates MLC and MYPT1, thereby causing actin-myosin contraction and regulating cancer cell movement." (PMID 39054484, 2024). "Our study has revealed a potent vulnerability of SMARCA4-mutant cancer cells to dual inhibition of ROCK1/2 and OXPHOS." (PMID 39345502, 2024). "The present study not only enriches the researches of chemerin in female malignant tumor development especially for omental metastasis but also reveals a novel mechanism of CMKLR1/RhoA/ROCK1-mediated EMT in invasion of metastasis of OC cells." (PMID 39104601, 2024). "A large role has recently been attached to the role of the CH domain in cancer, involving the Rho/ROCK1 signaling pathway." (PMID 37550786, 2023). "Pan-cancer analysis showed a correlation between low ROCK1 expression and SKCM as well as renal tumors (KIRP, KICH, and KIRC)." (PMID 37683138, 2023). "Currently, various ROCK1 inhibitors are used to reduce progression, metastasis and migration of a variety of cancers." (PMID 36781836, 2023). "We further investigate the correlation between ROCK1 expression and RNA modification genes in pan-cancer." (PMID 37683138, 2023). "Accumulating evidence suggests that dysfunction in ROCK1 can lead to various cancers, including bladder, breast, ovarian, gastric, colon and ovarian cancers." (PMID 36334145, 2022). "Among these genes, ROCK1 was first selected for further analysis due to its critical role in the progression of cancer." (PMID 35101080, 2022). "ROCK1, an effector kinase of Rho GTPases, plays a vital role in the regulation of cancer invasion and metastasis." (PMID 35997665, 2022). "Li and his colleagues suggested in a review that miR-148a inhibits the proliferation, apoptosis, metastasis, and invasion of cancer cells by directly targeting ROCK1 and BCL-2." (PMID 35997665, 2022). "miR-335 inhibits ROCK1 expression by binding directly to its untranslated region, resulting in decreased cell proliferation and migration in cancer development." (PMID 35651814, 2022). "Inhibition of ROCK1 using siRNA in NSCLC suppressed cancer cell proliferation and migration through downregulation of cyclin D and cyclin E119." (PMID 35379935, 2022). "miR-101, miR-139, miR-144, miR-202-5p, miR-150, miR-335 and miR-214-5p are examples of down-regulated miRNAs in this type of cancer that were shown to directly regulate expression of ROCK1." (PMID 36177350, 2022). "Increased matrix stiffness was correlated to Hras, RhoA, and rho-associated, coiled-coil-containing protein kinase 1 (ROCK1) upregulation, which are mechanosensor proteins that are implicated in migration and proliferation in cancers in general." (PMID 36005097, 2022). "Based on these studies, ROCK1 can be regarded as a marker of a poor prognosis in cancer and a promising target for cancer treatment." (PMID 35379935, 2022). "Previous studies have shown that ROCK1 regulates cancer cell motility, invasion, migration and metastasis." (PMID 35626071, 2022). "MiRNAs are able to regulate ROCK1 expression, and many miRNAs expression changes have been identified in cancer tissues." (PMID 35179516, 2022).
cancer (continued). "Inhibition of the downstream effector of Rho GTPases, ROCK1, by fasudil, H-1152 (dimethylfasudil), or Y27632 resulted in antiproliferative effects on cancer cells suggesting its promise as an AML treatment." (PMID 34638385, 2021). "Overexpression of miR-493-5p inhibited chemoresistance and cancer progression by downregulating ROCK1 expression in DDP-resistant NSCLC cells." (PMID 34537072, 2021). "Previous studies have found that multiple lncRNAs can affect cancer development by regulating ROCK1 via sponging the corresponding miRNAs, consistent with our findings." (PMID 34271873, 2021). "Upregulation of mRNA expression of ROCK1 was observed in thirty-nine AML cell lines from the Cancer Cell Line Encyclopedia (CCLE) database." (PMID 34638385, 2021). "MicroRNA-145 is a tumor suppressor gene that inhibits cancer cell growth, invasion, migration and enhances radio-or chemosensitivity to various cancers using its target site ROCK1." (PMID 33916931, 2021). "Rho-associated coiled-coil-containing protein kinase 1 (ROCK1), a downstream target of miR-148a, has been found oncogenic in many cancers by regulating cancer angiogenesis and metastasis." (PMID 34271873, 2021). "The PHKA1 catalyses the phosphorylation of serine, whereas ROCK1 catalyses that of serine/threonine in cancer development, progression and metastasis." (PMID 34199079, 2021). "The discovery of a potent ROCK1 inhibitor is a promising strategy to achieve the therapeutic goal against cardiovascular disease and carcinomas." (PMID 34434664, 2021). "ROCK1 participate in cancer biology not only through the interactions with proteins, but also by the cross-talk with non-coding RNAs, such as lncRNA." (PMID 32660450, 2020). "Taken together, these results suggested that the promotion of SW620 cancer cell invasiveness was dependent on NaV activity and indeed due to the inhibition of both ROCK-1 and ROCK-2." (PMID 32770034, 2020). "What is more, overexpression of RhoA or ROCK1 has contributed to malignant phenotype of cancers, such as ESCC." (PMID 32546278, 2020). "As a member of the Rho-related protein kinase (ROCK) family, ROCK1 plays an essential regulatory role in different types of cancer." (PMID 32219065, 2020). "In line with our assumptions, these cancer cells were also featured in general with lower miR-501-3p but higher ROCK1 transcripts compared to normal IOSE80 cells." (PMID 33168781, 2020). "As an oncogenic gene, ROCK1 is usually upregulated in the development of different types of cancers." (PMID 32660450, 2020). "Knocking down the expression of ROCK-1 increased the invasive capacity of SW620 cancer cells by a median factor of 1.42, and this effect was prevented by TTX." (PMID 32770034, 2020). "Recently, several studies revealed that long noncoding RNA DANCR and NEAT1 promoted ROCK1-mediated signaling pathways via decoying miR-335, leading to enhancement of cancer malignancy." (PMID 32219065, 2020). "Compared to the control, si/ROCK1 transfection reduced cell viability in an MTT assay, indicating that ROCK1 was necessary for cancer survival." (PMID 32554853, 2020). "As a well-studied key modulator in cancer, ROCK1 exerts its rolein cell proliferation, metastasis, and motility." (PMID 31939597, 2020). "ROCK1 plays a central role in cell polarity, migration and chemotaxis and is elevated in several cancers." (PMID 31578445, 2019). "Based on this rational approach, we have planned hybrid molecules containing covalently linked pharmacophoric units, present individually in compounds acting as inhibitors of the cancer protein targets tubulin, human topoisomerase II and ROCK1." (PMID 31197105, 2019). "Positive ROCK1 staining was seen in more than 90% of our 10,613 interpretable cancers, including 22% cancers with weak, 53% cancers with moderate and 18% with strong staining." (PMID 31557128, 2019). "It is reported that both ROCK1 and p190RhoGAP contribute to the promotion of cancer metastasis and EMT in various cancer cells." (PMID 31546735, 2019).